FABP6 (fatty acid binding protein 6)
Description:
Binds to bile acids and is involved in enterohepatic bile acid metabolism. Required for efficient apical to basolateral transport of conjugated bile acids in ileal enterocytes (By similarity). In vitro binds to bile acids in the order: deoxycholic acid > cholic acid > chenodeoxycholic acid and respective BA conjugation modifies affinities in the order taurine-conjugated > glycine-conjugated > unconjugated bile acids. Stimulates gastric acid and pepsinogen secretion (By similarity). [Isoform 2]: Essential for the survival of colon cancer cells to bile acid-induced apoptosis.
Synonyms: ILBP; I-15P; I-BABP; ILLBP; I-BAP; ILBP3; I-BALB
Tractability: Small molecule: a structure with a bound ligand is known; it has a high-quality binding pocket. Antibody: UniProt places it where antibodies can reach, with medium confidence. PROTAC: a small molecule that binds it is known.
Gene: Protein-coding gene on chromosome 5 (160,187,363 to 160,238,735, forward strand). Ensembl gene ENSG00000170231.
Subcellular location: Cytoplasm (Isoform 1); Membrane; Cytoplasm (Isoform 2)
Pathways (Reactome):
Metabolism: Recycling of bile acids and salts; Triglyceride catabolism
Signal Transduction: NR1H2 & NR1H3 regulate gene expression to control bile acid homeostasis
Gene Ontology:
Molecular function: fatty acid binding; lipid binding; lipid transporter activity
Biological process: fatty acid transport; lipid metabolic process; negative regulation of cell population proliferation; triglyceride catabolic process
Cellular component: cytoplasm; cytosol; nucleus; membrane
Genetic constraint (gnomAD): Loss-of-function variants: 10 observed, 12.34 expected, observed/expected ratio (o/e) 0.81, 90% interval 0.5 to 1.37. The upper end of that interval is the gene's LOEUF score, 1.37, which puts it in group 5 of 6, group 1 being the genes least tolerant of losing a copy. Missense variants: 140 observed, 148.61 expected, observed/expected ratio (o/e) 0.94, 90% interval 0.82 to 1.08. Synonymous variants: 67 observed, 58.59 expected, observed/expected ratio (o/e) 1.14, 90% interval 0.94 to 1.4.
Homologues: Orthologues: chimpanzee FABP6 (100% identical), rabbit FABP6 (83% identical), mouse Fabp6 (80% identical), rat Fabp6 (78% identical), macaque FABP6 (75% identical), pig FABP6 (74% identical), guinea pig FABP6 (72% identical), dog FABP6 (62% identical), zebrafish fabp6 (57% identical), tropical clawed frog fabp6 (55% identical), Caenorhabditis elegans lbp-7 (22% identical), Caenorhabditis elegans lbp-8 (19% identical). Paralogues in human: FABP1 (35% identical), RBP2 (30% identical), FABP3 (28% identical), CRABP2 (27% identical), CRABP1 (27% identical), FABP4 (26% identical), FABP7 (26% identical), RBP1 (26% identical), FABP2 (25% identical), RBP5 (25% identical), RBP7 (24% identical), FABP12 (23% identical), and 3 more.
Diseases named in the same sentence as FABP6 in open-access papers:
FABP6 is named in the same sentence as 48 diseases in open-access papers, as found by Europe PMC text mining. Sharing a sentence is not in itself a finding about the gene and the disease. The quoted sentences say what the papers report.
colorectal cancer (15 papers, 2016 to 2025). A primary or metastatic malignant neoplasm that affects the colon or rectum. "The expression of Fabp6 and other genes in its family has been found to be associated with colorectal cancer, and its expression is strongly correlated with cell migration and the immune response." (PMID 38730628, 2024). "Recent studies have indicated that elevated levels of FABP6 are associated with the initiation and development of colorectal cancer by regulating the NF-κB pathway." (PMID 34150630, 2021). "In colorectal cancer, FABP6 is negatively correlated with immune infiltration, and its downregulation can enhance tumor immunogenicity and promote the recruitment of CD8+ T cells." (PMID 41019085, 2025). "FABP6 is significantly overexpressed in colorectal cancer tissues and serum, showing a clear difference compared with normal tissues, and can serve as a potential diagnostic biomarker." (PMID 40717587, 2025). "FABP1 and FABP6 are strongly expressed in colorectal cancer tissues, with overexpression of FABP6 protein was found to be associated with poorer overall survival (OS) in colorectal cancer patients." (PMID 35783014, 2022). "FABP6 was significantly correlated with “ubiquinone metabolism”, “l-lysine metabolism”, and “role of microRNAs in cell proliferation in colorectal cancer” in the development of CRC." (PMID 34680577, 2021). "Fatty acid-binding protein 6 (FABP6) is a bile acid carrier protein that is overexpressed in colorectal cancer." (PMID 34685761, 2021). "In this work, they observed that the expression of FABP6 was higher in primary colorectal cancers and adenomas than in normal epithelium, thus suggesting that FABP6 plays an important role in early carcinogenesis." (PMID 32640984, 2020). "Combined detection of FABP6 with CEA can improve the sensitivity of colorectal cancer diagnosis." (PMID 40717587, 2025). "A FABP6 has been reported to be a cancer-related protein in colorectal cancer." (PMID 34685761, 2021). "In addition, we found that FABP6 was significantly correlated with the “role of microRNAs in cell proliferation in colorectal cancer” in the development of CRC using MetaCore analysis." (PMID 34680577, 2021). "Interestingly, levels of FABP6 expression significantly differ depending on the histological type of colorectal cancer." (PMID 33809784, 2021). "It was reported that the FABP5 and FABP6 were overexpressed and might play promoting roles in colorectal cancer." (PMID 27779102, 2016). "FABP6 might be a viable therapeutic target for colorectal cancer." (PMID 34680577, 2021). "FABP6 downregulates MHC-I molecules expression and reduces CD8+ T cell infiltration, thereby promoting immune evasion in colorectal cancer." (PMID 40717587, 2025). "FABP6, hypermethylated SFRP1, XDH, PLAU, ADH1C, HSD17B2, and SPP1 have been identified more as a colorectal cancer biomarker than as a therapeutic target at present." (PMID 34381520, 2021).
colon cancer (6 papers, 2020 to 2025). "Bile-acid concentrations, particularly secondary bile acids, are known to be higher in colon adenomas, whereas bile acids promote enhanced FABP6 expression in colon cancer cell lines in vitro." (PMID 34680577, 2021). "Based on our findings, the FABP6 gene and, specifically, its protein products, are proposed as therapeutic targets for the development of colon cancer." (PMID 32640984, 2020). "Furthermore, the involvement of FABP6 in the development of colon cancer has been addressed in previous publications." (PMID 32640984, 2020). "Finally, and after the evidence gathered, both in our own experiments and in previous work, the FABP6 gene and the drug Abemaciclib are proposed as a possible targets and treatment, respectively, in colon cancer." (PMID 32640984, 2020). "FABP6 is overexpressed in colon cancer and may play an important role in early carcinogenesis." (PMID 32843852, 2020). "The results of our ML and differential expression experiments have first shown the FABP6 gene as a possible new cancer biomarker due to its specificity in colonic tumour tissue and no expression in healthy adjacent tissue." (PMID 32640984, 2020). "In this work, we report that this drug could also be used for the treatment of colon cancer, after subsequent experimental validations, due to its strong interaction with all the protein PDB structures of the FABP6 gene." (PMID 32640984, 2020).
bladder cancer (5 papers, 2020 to 2026). "However, in another study, FABP6 was found to promote bladder cancer cell growth and cisplatin resistance." (PMID 38910160, 2024). "A potential signaling role for FABP6 is further suggested by studies in bladder cancer and human glioblastoma cells, where knockdown of FABP6 led to reduced cell growth and tumor invasiveness accompanied by reduced cell motility and migration and by cell cycle arrest." (PMID 37207357, 2023). "The current study aimed to investigate the role of FABP6 in human bladder cancer cells." (PMID 35216267, 2022). "The aim of this study was to evaluate the role of fatty acid binding protein 6 (FABP6) in proliferation and migration in human bladder cancer cells." (PMID 35216267, 2022).
breast carcinoma (4 papers, 2016 to 2021). "Next, we determined the correlation between increased CD36 expression and the various FABP genes (FABP1, FABP2, FABP3, FABP4, FABP5 and FABP6) in the TCGA breast cancer cohort." (PMID 34561446, 2021). "When analysed by Western blot, a single 14 kDa FABP6 band was detected in all prostate cell lines as well as a positive control MCF7 breast cancer cells." (PMID 27779102, 2016). "The roles of other IRGs in our signature in breast cancer, including IGHE, SCG2, NPR3 and FABP6, require further clarification." (PMID 33216733, 2020).
adenoma (3 papers, 2020 to 2021). A neoplasm arising from the epithelium. "Expression studies demonstrated differential expression of Fabp6 between Min/J and Min/D, and the variant correlates with adenoma multiplicity in backcrossed mice." (PMID 32600361, 2020). "Tumor number assessment that was performed blinded for genotype showed a significant correlation with the Fabp6 variants, where mice that were homozygous for the Min/D variant had the highest adenoma susceptibility." (PMID 32600361, 2020). "Decreased expression of Fabp6 in normal ileal epithelium associated with increased adenomagenesis in Min/D mice, as well as a significant association between the Fabp6 variant and SI adenoma multiplicity in N2 mice, support the proposed role for Fabp6 in tumor initiation." (PMID 32600361, 2020). "Thus, we observed differential Fabp6 expression between the Min/J and Min/D lineages associated with the validated upstream insertion in Min/D mice, and further associated this variant with SI adenoma susceptibility in N2 mice." (PMID 32600361, 2020). "In this present study, FABP6 mRNA expression was found to be significantly higher in the progression from normal tissues to adenomas and CRC." (PMID 34680577, 2021). "We validated the Fabp6 variant detected by WGS and further interrogated whether Fabp6 is a possible modifier of adenoma susceptibility." (PMID 32600361, 2020).
gastric cancer (3 papers, 2020 to 2025). A primary or metastatic malignant neoplasm involving the stomach. "In diagnostics, while FABP1 combined with TRIB3 can improve the sensitivity of early gastric cancer diagnosis, and FABP6 combined with CEA can enhance CRC diagnostic efficacy, the specificity of single biomarkers and expression heterogeneity across different cancer types limit clinical application." (PMID 40717587, 2025). "FABP6 is regulated by the transcription factor REST and participates in gastric cancer progression by influencing autophagy and the Akt/mTOR pathways." (PMID 41019085, 2025).
glioma (3 papers, 2021 to 2024). A benign or malignant brain and spinal cord tumor that arises from glial cells (astrocytes, oligodendrocytes, ependymal cells). "Conversely, FABP6, which is upregulated in gliomas compared with control brain tissue, has been implicated in reduced invasion and angiogenesis upon FABP6 knockdown." (PMID 39588145, 2024). "Other fatty acid-binding proteins such as FABP3, FABP5, FABP6 and FABP7 have been also implicated in glioma migration or invasion." (PMID 37120445, 2023). "For targeting FABP6 in glioma patient therapy, specific FABP6 inhibitors or research into other modulators of the FABP6 pathway is recommended." (PMID 34685761, 2021). "In our study, the knockdown of FABP6 resulted in the inhibition of the invasion, migration, and angiogenesis in glioma." (PMID 34685761, 2021). "Our results suggest targeting FABP6 combined with TMZ can ameliorate glioma proliferation and migration." (PMID 34685761, 2021). "After the knockdown of FABP6, a decrease in the migration and invasion abilities of glioma cells was observed." (PMID 34685761, 2021). "This is the first study that revealed the impact of FABP6 on the invasion, angiogenesis, and progression of glioma." (PMID 34685761, 2021). "Immunohistochemical analysis revealed that FABP6 expression was higher in glioma than in normal brain tissue." (PMID 34685761, 2021). "Accordingly, this is the first study to investigate the role of FABP6 in the progression of glioma." (PMID 34685761, 2021). "FABP6 expression was significantly higher in the glioma cell lines." (PMID 34685761, 2021). "In addition, the levels of the tissue inhibitors of metalloproteinases (TIMP)-1 and TIMP-2 decreased after FABP6 reduction in glioma cells." (PMID 34685761, 2021). "Taken together, the results of this study indicate that FABP6 may interact with the VEGF/VEGFR signaling pathway to control angiogenesis in gliomas; however, this needs to be investigated in future studies." (PMID 34685761, 2021). "Previous studies have revealed a link between bile acids, FABP6, and colorectal carcinogenesis in animal models; however, whether the effect of FABP6 on glioma remains unknown." (PMID 34685761, 2021). "Next, the endothelial network formation was analyzed after FABP6 knockdown in glioma cells." (PMID 34685761, 2021). "Moreover, the expression levels of VEGFR1 and VEGFR2 were significantly reduced after FABP6 inhibition in glioma cells." (PMID 34685761, 2021). "According to our results, the expression of FABP6 in gliomas was higher than normal tissue." (PMID 34685761, 2021). "As the phosphorylation of extracellular signal-regulated kinase (ERK) and c-Jun NH2-terminal kinase (JNK) promotes glioma cell invasion and migration, we examined the p-ERK and p-JNK expression after FABP6 knockdown." (PMID 34685761, 2021). "After knockdown of FABP6, angiogenesis was attenuated in HUVECs, accompanied by the decreased expression levels in VEGF in the CM and VEGFRs in glioma cells." (PMID 34685761, 2021). "FABP6 reduction did not affect the survival rate of LN229 glioma cells compared to that of control cells." (PMID 34685761, 2021). "The expression of FABP6 was found to be elevated in the neoplastic brain tissue and was not proportional to the grade of the glioma." (PMID 34685761, 2021). "In our study, p-JNK and p-p65 were decreased as FABP6 was reduced, which may inhibit MMP-2 and cathepsin B expression in glioma." (PMID 34685761, 2021).
Obesity (3 papers, 2019 to 2024). Accumulation of substantial excess body fat. "The expansion of the Firmicutes phylum we observed in male Fabp6−/− mice fed the WSD at the expense of other phyla is also distinct from that of female Fabp6−/− mice fed the same diet, and this is concordant with the pattern of change known to promote obesity." (PMID 33527741, 2021).
COVID-19 (2 papers, 2023 to 2024). A disease caused by infection with severe acute respiratory syndrome coronavirus 2. "Overall, this study highlights the significant roles of TRUB1, PLEKHA7, and FABP6 in the development of depression associated with COVID-19." (PMID 39588145, 2024). "In summary, this research highlights the roles of TRUB1, PLEKHA7, and FABP6 as hub genes, the underlying pathways and TF–miRNA networks, and the potential impact of these genes on immune cell activity in the development of depression and COVID-19." (PMID 39588145, 2024). "In this study, the genes TRUB1, PLEKHA7, and FABP6 emerged as central hubs potentially contributing to the pathogenesis of both depression and COVID-19." (PMID 39588145, 2024). "Our findings revealed that TRUB1 and PLEKHA7 expression was decreased, whereas FABP6 expression was increased in both the depression group and the COVID-19 patient group compared with the control group." (PMID 39588145, 2024). "Among the 12 patients who did not generate detectable antibodies, we observed a significantly elevated level of IL17C and a protein in the PPAR signaling pathway, namely, FABP6, compared to patients with COVID-19 with detectable antibodies." (PMID 37047248, 2023).
metabolic syndrome (2 papers, 2013 to 2019). A cluster of metabolic risk factors for CARDIOVASCULAR DISEASES and TYPE 2 DIABETES MELLITUS. "It has been shown that FABP6 is associated with type II diabetes therefore suggesting an association of variants between fatness and type II diabetes susceptibility, as well as the role of FABPs in fat absorption and in the development of metabolic syndrome." (PMID 24225222, 2013).
rectal adenocarcinoma (2 papers, 2020 to 2021). "We also present in boxplot visualizations comparisons of the expressions of FABP genes in normal, colon adenocarcinoma (COAD), and rectal adenocarcinoma (READ) tissues, which showed that the FABP1, FABP4, and FABP6 genes had significantly different expression levels in normal and CRC tissues." (PMID 34680577, 2021). "This does not occur in the READ cohort (rectum adenocarcinoma), which presents high levels of FABP6 in tumour tissues throughout the sample." (PMID 32640984, 2020).
bladder neoplasms (1 paper, 2022). "In addition, bladder neoplasms (orange) showed higher FABP6 expression levels than normal tissues (blue) in the Gene Expression Profiling Interactive Analysis (GEPIA)." (PMID 35216267, 2022).
brain cancer (1 paper, 2025). A primary or metastatic malignant neoplasm affecting the brain. "In addition, specific FABP subtypes exhibit tissue- and context-dependent functions, with FABP4, FABP5, FABP6, and FABP7 being the most extensively studied in breast, liver, colorectal, and brain cancers." (PMID 40717587, 2025).
colorectal tumor (1 paper, 2019). "Immunohistochemistry showed that FABP4 and FABP6 were mainly distributed in the cytoplasm of human colorectal tumor tissues, and only a small amount distributed in adjacent tissues." (PMID 31651326, 2019). "The protein expressions of FABP4 and FABP6 were observed in colorectal tumor tissues and adjacent tissues by immunohistochemistry and western blot, respectively." (PMID 31651326, 2019). "Western blot analysis showed that the protein expression levels of FABP4 and FABP6 in colorectal tumor tissues were higher than those in adjacent tissues (FABP4: 1.103 ± 0.529 vs 0.746 ± 0.296, P < 0.001; FABP6: 0.988 ± 0.225 vs 0.521 ± 0.156, P = 0.002)." (PMID 31651326, 2019).
enteritis (1 paper, 2021). Inflammation of the small intestine. "Similarly, FABP6 was significantly increased in the intestine of gilthead seabream fed a combination of carvacrol, thymol, and a prebiotic, while this gene was downregulated in response to enteritis induced by a parasitic pathogen." (PMID 33746962, 2021).
esophageal carcinoma (1 paper, 2024). A primary or metastatic malignant neoplasm involving the esophagus. "In our preceding investigation, we conducted exploratory analysis utilizing single-cell data from esophageal carcinoma, revealing a regulatory influence of FABP6 on Treg cells, demonstrating a positive correlation." (PMID 38277205, 2024). "Overall, this single-cell sequencing study sheds light on tumor heterogeneity and identifies FABP6 as a potential driver of esophageal carcinoma progression and immunotherapy resistance, meriting further investigation as both a predictive biomarker and therapeutic target." (PMID 38277205, 2024).
esophageal tumor (1 paper, 2024). "The analysis of the TCGA database confirmed higher expression of FABP6 in esophageal tumor tissue, and patients with high FABP6 expression exhibited poorer survival." (PMID 38277205, 2024). "We analyzed the expression of FABP6 in normal esophageal tissue and esophageal tumor tissue through the TCGA and GTEx database and found that esophageal tumor tissue had a higher expression level." (PMID 38277205, 2024).
essential hypertension (1 paper, 2019). Hypertension that presents without an identifiable cause. "As for FABP6, it played an important role in the transport of bile acids, and bile acids are involved in the pathogenesis of essential hypertension as an endogenous inhibitor of 11β-hydroxysteroid dehydrogenase.Thus, these findings can explain why FABP6 is related to SBP and DBP in our study." (PMID 31651326, 2019).